CD44 (CD44 molecule (IN blood group))
Diseases named in the same sentence as CD44 in open-access papers (continued):
Sharing a sentence is not in itself a finding about the gene and the disease.
osteosarcoma (continued). "Moreover, deletion of CD44 in osteosarcoma cells led to significantly reduced Abcb1b mRNA levels." (PMID 35955749, 2022). "We also showed that the shortest isoforms of CD44, so called CD44s, which does not contain any sequences encoded by alternatively spliced variant exons, was sufficient to confer resistance to doxorubicin in osteosarcoma cells." (PMID 35955749, 2022). "Previous studies on the role of CD44 in osteosarcoma mostly used it as a cancer stem cell marker to evaluate the stem cell status of osteosarcoma, or it could be used as an evaluation protein for pulmonary metastasis of osteosarcoma." (PMID 35264209, 2022). "However, recent studies, including other meta-analyses of 548 osteosarcoma patients from nine studies, have concluded that CD44 expression may predict survival, metastasis recurrence, and drug resistance." (PMID 35785191, 2022). "Developing strategies to target CD44 may improve the clinical outcome of osteosarcoma." (PMID 26079799, 2015). "Therefore, CD44 may indeed be a critical modulator in the metastatic and recurrent progression of osteosarcoma." (PMID 26079799, 2015). "Additionally, upregulation of CD44 accelerated lung metastasis in mouse osteosarcoma models." (PMID 26079799, 2015). "Considering the clinical data we obtained that osteosarcoma patients who responded poorly to chemotherapy presented stronger CD44 levels, it is hypothesized that miR-199a-3p may attenuate drug resistance through inhibition of CD44 expression." (PMID 26079799, 2015). "In vitro studies have demonstrated that targeting CD44 with CRISPR/Cas9 significantly reduces its expression, leading to decreased cell proliferation and migration in osteosarcoma cell lines." (PMID 40283955, 2025). "The human osteosarcoma cell lines MNNG/HOS and 143B were both highly metastatic, and CD44 was reported to be knocked out by CRISPR/Cas9." (PMID 38783892, 2024). "Previous studies have also found that CD44, CD40, PDCD1LG2, LAG3, and HAVCR2 can be immunotherapeutic targets for osteosarcoma." (PMID 38071320, 2023). "For example, in nude mice intratibial xenograft model performed with Saos-2 osteosarcoma cell line, CD133+/CD44+ cells were potentially more metastatic." (PMID 35785191, 2022). "HA acts as a ligand targeting osteosarcoma cells through CD44, and the binding of HA-CD44 and acid-sensitive detachment of PEG can realize specific targeting and drug release on osteosarcoma cells." (PMID 35694235, 2022). "Strikingly, the expression of stemness biomarkers was downregulated in osteosarcoma cells after lncRNA SOX2-OT knockdown, including ALDH1, Nanog, Oct4, CD44 and CD133." (PMID 35252166, 2022). "This agrees with in vitro studies carried out in different osteosarcoma cell lines (KHOS doxorubicin resistant, U2-OS doxorubicin resistant, MNNG/HOS, and 143B) that demonstrated that CD44 promotes cell migration, cell invasiveness, and drug resistance." (PMID 35785191, 2022). "Our RT-qPCR data revealed that mRNA levels of stemness-related markers, such as NANOG, SOX2, CD44, and CD133, were significantly downregulated in JAGGED1-silenced osteosarcoma cells." (PMID 34725550, 2021). "HIF2Put promotes the growth of osteosarcoma cells by upregulating the expression of stem cell-related genes OCT4, SOX4 and CD44." (PMID 34048366, 2021). "By the way, CD117, IBSP (Stro-1), ID1, SOX9, CD24, CD44 and THBS-1 were also reported to affect osteosarcoma growth and stemness." (PMID 34828292, 2021).
osteosarcoma (continued). "The results in osteosarcoma cell lines with constitutive knockout of CD44 gene by CRISPR/Cas9 system verified that CD44 mediates migration, invasion, proliferation and drug resistance to doxorubicin in osteosarcoma cells." (PMID 31921125, 2019). "Our data highlighted that KMT2C modulated the gene expression of CD44 and FN1 probably influencing the attachment of osteosarcoma cells to ECM, a necessary step for osteosarcoma cells to metastasize." (PMID 30093974, 2018). "However, the prognostic value of CD44 in osteosarcoma has remained largely unknown." (PMID 26079799, 2015). "Therefore, CD44 may become a therapeutic target in osteosarcoma." (PMID 26079799, 2015). "Several reports have claimed that surface markers for mesenchymal stem cells such as CD44 and CD90 were expressed in human osteosarcomas." (PMID 22852096, 2012). "In addition, through CellChat analysis,we found that HVECs in osteosarcoma secrete molecules such as MIFand APP, which interact with macrophage surface molecules or complexessuch as CD74 and CD44." (PMID 40834268, 2025). "The same study also identified differential regulation of several apoptosis-related genes in CD44-positive and -negative primary osteosarcomas." (PMID 37958796, 2023). "Besides the STAT3-EMT and PI3K/AKT-FOXO1 signaling pathways, we found that new signals including CD44 and CXCL8 were also involved in DS−1-induced physiological regulation in human osteosarcoma U−2 OS cells." (PMID 35744840, 2022). "Expression of several other genes, including Appl2 was not significantly different in Cd44-positive and Cd44-negative osteosarcoma cells, although they were found to be differentially expressed in the tissue." (PMID 35955749, 2022). "Doxorubicin-treated Cd44-positive osteosarcoma cells formed significantly larger colonies than their Cd44-negative counterparts, independent of medium supplementation with serum." (PMID 35955749, 2022). "It was revealed that VIRMA knockdown could suppress the expression of stem factors Notch1, Oct4, Nanog and CD44 in osteosarcoma cells, which suggested that VIRMA promoted osteosarcoma progression by activating Notch signaling pathway." (PMID 33731118, 2021). "In addition, osteoblast and osteosarcoma cell lines KHOS and U-2OS exhibit significantly higher expression of CD44." (PMID 29747682, 2018). "In order to evaluate whether CD44 is a direct target of miR-199a-3p, osteosarcoma cell lines U-2OS and KHOS were transfected with miR-199a-3p mimic, and the effects on CD44 expression were determined." (PMID 26079799, 2015). "The present meta-analysis showed that high CD44 expression did not indeed predict poor survival and metastasis in patients with osteosarcoma." (PMID 25112408, 2014). "However, the levels of CD44 and CD90 expression in MFH were very similar to MSCs compared to osteosarcoma." (PMID 22852096, 2012). "In addition, the results of a meta-analysis showed that knocking out CD44 using the CRISPR/Cas9 system could inhibit invasion, metastasis, and spheroid formation in osteosarcoma cells." (PMID 35715750, 2022).
osteosarcoma (continued). "By real-time qRT-PCR we could confirm that the levels of Perp mRNA were highly upregulated in Cd44-negative osteosarcoma cells when compared with Cd44-positive cells." (PMID 35955749, 2022). "Our results indicate that CD44 increases the resistance of osteosarcoma cells to doxorubicin by up-regulating the levels of multidrug resistance (MDR) 1 protein expression, and suggest the role of proteolytically released CD44 intracellular domain, and hyaluronan interactions in this process." (PMID 35955749, 2022). "Additionally, attenuation of CD44 expression sensitized these cell models against osteosarcoma chemotherapy with doxorubicin but not methotrexate and cisplatin." (PMID 29371972, 2017). "CD44 may not be a useful marker to predict prognosis of osteosarcoma." (PMID 25112408, 2014). "The result indicated that positive expressions of CD44 did not predict neoplasm metastasis (RR = 1.36, 95% CI: 1.00–1.84, P = 0.50), and higher expression of CD44 could not predict poorer survival in osteosarcoma with the pooled HR of 0.55 (95% CI: 0.27–1.13, P = 0.47)." (PMID 25112408, 2014). "Positive expressions of CD44 did not predict neoplasm metastasis (RR = 1.36, 95% CI: 1.00–1.84, P = 0.50), and the results indicated that higher expression of CD44 could not predict poorer survival in osteosarcoma with the pooled HR of 0.55 (95% CI: 0.27–1.13, P = 0.47)." (PMID 25112408, 2014). "However, since the majority of osteosarcoma cells are positive for many of these proposed MSC markers, markers such as CD90, CD44, and CD29 may not be useful markers to isolate the osteosarcoma CSC." (PMID 20979639, 2010).
cervical carcinoma (61 papers, 2011 to 2026). A carcinoma arising from either the exocervical squamous epithelium or the endocervical glandular epithelium. "CD44 is highly expressed on the surface of cervical cancer‐associated cells within the tumour microenvironment (TME), including immune cells, cancer‐associated fibroblasts (CAFs), and cancer stem cells (CSCs)." (PMID 40888184, 2025). "The transmembrane glycoprotein cluster of differentiation 44 (CD44), a marker associated with cancer stem cells (CSCs), has emerged as a critical mediator of both processes in cervical cancer." (PMID 40888184, 2025). "This study has an important and novel finding: Taiwanese women with cervical cancer who carry genotypes GG/AG in CD44 genetic variant rs187115 have poorer 5-year survival rates than those with AA." (PMID 38903932, 2024). "Higher expression of CD44 in advanced tumors has been recorded in several types of malignancies, such as in lymphomas, and gastric and cervical carcinomas, possibly associated with poor prognosis." (PMID 36831554, 2023). "High CD44 expression in HPV-16 positive cervical cancer has been associated with increased metastasis, high colony formation capacity, and resistance against radiation therapy." (PMID 36712656, 2022). "A summarized representation of studies encompassing CD44's pathogenic role in cervical cancer." (PMID 40888184, 2025). "(2021) identified that increased CD44 expression levels in cervical cancer cells were commonly associated with a more aggressive tumor phenotype, as well as highlighting a correlation between elevated CD44 levels and reduced overall survival in patients with cervical cancer." (PMID 40888184, 2025). "Furthermore, aberrant cervical cancer stem cell (CCSC) CD44 overexpression is frequently linked to metastasis in cervical cancer patients." (PMID 40888184, 2025). "Moreover, the relationships between CD44 genetic variants and clinicopathological parameters of cervical cancer patients were assessed." (PMID 38903932, 2024). "Therefore, we designed this research to relate CD44 genetic polymorphisms to cervical carcinogenesis, as well as clinicopathological parameters and the 5-year survival rate of Taiwanese cervical cancer patients." (PMID 38903932, 2024). "Noteworthily, CD44 genetic variants were related to 5 years survival of cervical cancer patients." (PMID 38903932, 2024). "In addition to univariate Kaplan-Meier curve model analysis, multivariate Cox proportional hazard analysis also revealed that cervical cancer patients with genotypes AG/GG had a higher risk of poor 5-year survival rates compared to AA in CD44 polymorphism rs187115." (PMID 38903932, 2024). "Before gaining an understanding of resveratrol's chemo‐sensitizing potential for cervical cancer cells, it is essential to first predict a possible relationship between CD44 and resveratrol in the context of cervical cancer." (PMID 40888184, 2025). "Although studies surrounding resveratrol's anti‐cervical cancer potential exist, studies investigating resveratrol's relationship with CD44‐promoting metastasis and chemoresistance mechanisms in cervical cancer remain to be fully elucidated." (PMID 40888184, 2025). "CD44 has been consistently implicated in promoting drug resistance, epithelial‐to‐mesenchymal transition (EMT), and stemness in cervical cancer." (PMID 40888184, 2025). "Not only are CSCs recognized as a potential prognostic marker for cervical cancer patients, but they also facilitate CD44's communicative crosstalk between the ECM and the CSC surface." (PMID 40888184, 2025). "Current findings suggest a promising therapeutic avenue for combining resveratrol with carboplatin to overcome CD44‐mediated treatment resistance and metastasis in cervical cancer." (PMID 40888184, 2025). "This review aims to critically evaluate current evidence on the role of CD44 in cervical cancer progression, metastasis, and treatment resistance." (PMID 40888184, 2025).
cervical carcinoma (continued). "Flow cytometry revealed that the KD of CBX2 in cervical cancer cells resulted in decreased percentages of CD44+ population." (PMID 39793896, 2025). "Knowing this, it can be inferred that resveratrol possesses the potential to inhibit CD44‐induced metastasis and treatment resistance within cervical cancer cells, whilst indirectly enhancing sensitivity to chemotherapy drugs such as carboplatin." (PMID 40888184, 2025). "Overall, HINPs have the potential to enhance NIR fluorescence image-guided surgery by assisting in the visualization of CD44-positive cervical cancer." (PMID 38444688, 2024). "Although little evidence supports the direct role CSCs and ICIs have on cervical cancer specifically, potential conclusions can be drawn based on the known presence of high CD44 levels within cervical tumours." (PMID 38816670, 2024). "Several studies support the use of specific biomarkers (carcinoembryonic antigen, squamous cell carcinoma antigen, and CD44) to identify early-stage cervical cancer and, therefore, offer a better prognosis for patients." (PMID 39049119, 2024). "Further research is needed to understand the role of metastasis-inducing EMT in advanced-stage cervical cancer, particularly in conjunction with CD44 and immune checkpoints." (PMID 38816670, 2024). "Combining SPP1 and CD44 can serve as an early biomarker for cervical cancer diagnosis and prognosis." (PMID 38346944, 2024). "Such targets include the metastatic-promoting stem cell marker, CD44, which is abundant in cervical cancer cells and is common to both chemoresistance and metastatic mechanisms." (PMID 38816670, 2024). "In cervical cancer, high CD44 expression in HPV16 (human papillomavirus type 16) positive cell lines was associated with resistance to radiation therapy, high clonogenic capacity and advanced metastasis." (PMID 37283735, 2023). "Overexpression of LncRNA HOXA11-AS promotes sphere formation, CSC markers CD133+/CD44+ and self-renewal of cervical cancer cells." (PMID 36685972, 2022). "The aim of this study was to develop hyaluronic acid coated, thiolated chitosan nanocarriers using green synthesis approach, for CD44 targeted delivery and sustained release of Cisplatin in cervical cancer cells." (PMID 36712656, 2022). "The aim of this research was to formulate a ThCs based nano drug delivery system (DDS), surface functionalized with HA for CD44 targeted delivery of Cis inside cervical cancer cells." (PMID 36712656, 2022). "CSCs existence in cervical cancer with CD44+CK17+/sphere-forming and express stemness-related genes (Oct-4, Sox2 and so on)." (PMID 36685972, 2022). "In the present study, we developed a new drug delivery system of biodegradable polymer-based polymeric nanoparticles via a layer-by-layer (LBL) self-assembly method for the HER3/CD44 dual-targeted PDT/CAP combinatory treatment of HPV-positive cervical cancer." (PMID 33504007, 2021). "It has been shown that in lymphomas, as well as in gastric and cervical carcinomas, high CD44 expression is correlated with more advanced tumor stage and possibly with poor prognosis." (PMID 34837915, 2021). "Then, we confirmed that the Wnt/β-catenin pathway was stimulated by Srx in HeLa, SiHa and C33A cells, with activation of CD44—its target genes—resulting in the promotion of invasion and migration in cervical cancer cell lines." (PMID 28448437, 2017). "OCT1 is likely to provide a theoretical evidence for elucidating the pathogenesis of cervical cancer if the mechanisms of CD44 regulating OCT1 expression are clarified in cervical cancer." (PMID 24932254, 2014). "We used human cervical cancer HeLa cells because this cell line has been successfully used to demonstrate CRD-BP-mediated stabilization of CD44 mRNA." (PMID 24622399, 2014). "Previous studies suggested that CD44+CK17+/sphere-forming cervical cancer cells display stem cell properties." (PMID 22580387, 2012).